ARID1A (AT-rich interaction domain 1A)
Diseases named in the same sentence as ARID1A in open-access papers (continued):
Sharing a sentence is not in itself a finding about the gene and the disease.
tumor (continued). "Inhibiting the ATM/Chk2 DNA damage checkpoint pathway triggers replication stress and the accumulation of cytosolic DNA, activating the innate immune response mediated by the DNA sensor STING in ARID1A‐deficient tumours." (PMID 38041544, 2023). "ARID1A (AT-Rich Interaction Domain 1A) is a bona fide tumor suppressor gene, given its loss of function in many different tumors." (PMID 37109525, 2023). "The most commonly mutated component of this chromatin remodeling complex is the ARID1A gene, which demonstrates an aberrant variant in 6% of all malignancies, suggesting a broad tumor suppressor function." (PMID 37686496, 2023). "In this review we summarize the current knowledge on the role of ARID1A as tumor suppressor or oncogene in different tumor types and discuss the strategies for treating ARID1A mutated cancers." (PMID 36890819, 2023). "PD-L1 protein was also highly expressed in ARID1A-deficient tumor cells, which predicts the level of the response to ICI treatment in lung cancer." (PMID 37371564, 2023). "In the MLH1-lost subgroup, ARID1A loss occurs in the early stages of tumor development, but only in EBV- and MLH1+ GCs the loss of ARID1A expression was associated with prognostic features." (PMID 36890819, 2023). "The median number of mutations in ARID1A+ population was higher compared to ARID1A– population (6 vs. 4), as well as tumor mutational burden (TMB) [20 mutations/megabase (mut/Mb) vs. 1.26 mut/Mb]." (PMID 37711591, 2023). "High-throughput sequencing of EBVaGC has shown a high frequency of PIK3C and ARID1A mutations, both of which are associated with tumor development." (PMID 37000076, 2023). "The use of irradiation in combination with PARP inhibitors in model mice deficient for ARID1A acts synergistically, enhancing cytotoxicity in ARID1A-negative tumor cells." (PMID 37175555, 2023). "Murine models of ARID1A-deficient cells lead to reduction of SWI/SNF regulation of enhancers associated with tumor generation." (PMID 37888109, 2023). "The loss of ARID1A expression was associated with a larger tumor size, nuclear grade, and higher stage." (PMID 36890819, 2023). "We further noted that mutations targeting TBX3 were confined to EA patients and those targeting the FBXW7 tumor suppressor to AA patients whereas mutations in the ARID1A gene were distinctively enriched among Kenyan patients." (PMID 37902422, 2023). "This review will examine the molecular mechanisms of ARID1A as a tumour suppressor, the role of ARID1A in human cancers, and some of the synthetically lethal strategies that are in the process of development to target tumours of ARID1A mutations." (PMID 38275587, 2023). "At‐rich interaction domain 1A(Arid1a), a non‐catalytic subunit of the chromosomal remodelling complex, is one of the most commonly mutated genes in tumours and plays a critical role in enhancer mediated gene regulation and chromatin epigenetic inheritance." (PMID 36916004, 2023). "Since Chk2 is a downstream kinase of ATM, inhibition of the ATM/Chk2 axis in ARID1A deficient cells led to replication stress, increased tumor-infiltrating lymphocytes, and a STING-mediated innate immune response resulting in longer patient survival." (PMID 36123603, 2022). "Meanwhile, because it was reported that loss of ARID1A can lead to high CD8+ T-cell infiltration via the increased tumor mutation burden, we further determined the number of CD8+ T cells in GBC specimens by IHC." (PMID 35198440, 2022). "On the other hand, proliferation of the tumor was characterized by ARID1A missense mutation in LUSC, thus influencing the T stage as well." (PMID 35783357, 2022). "Although loss of tumor suppressors such as ARID1A are difficult to target directly, oftentimes these losses result in therapeutic vulnerabilities that can be targeted through a synthetic lethality approach." (PMID 35852858, 2022). "Studies have shown that epigenetic-related gene mutations can lead to increased TMB in tumor cells, such as ARID1A and KMT2D." (PMID 36479108, 2022).
tumor (continued). "ARID1A is commonly classified as a tumor suppressor, and low ARID1A expression is associated with a poor prognosis in multiple cancers." (PMID 35198440, 2022). "Inactivation of ARID1A correlated with tumor metastasis and was common in liver fluke-associated CCA." (PMID 35205774, 2022). "Loss of ARID1A function compromises DNA damage repair and increases the reliance of tumor cells on ATR-dependent DNA repair pathways." (PMID 36249060, 2022). "One nonsense mutation (p.Q537X) in ARID1A was identified in both the peritoneal fluid ctDNA and tumor gDNA of EC2." (PMID 35626111, 2022). "As a subunit of the BAF complex, ARID1A functions as a bona fide tumor suppressor and is mutated in approximately 8% of all human cancers." (PMID 35715442, 2022). "SAHA is a pan-HDAC inhibitor, and it was found to significantly inhibit the progression of ovarian cancer-harboring ARID1A mutations and to significantly prolong the survival of tumor-inoculated mice." (PMID 36361605, 2022). "ARID1A deficiency has been related to a compromised mismatch repair pathway, expression of programmed cell death ligand 1 (PD-L1) and tumor mutational burden." (PMID 35565222, 2022). "The recent success of PARP inhibitors in treating homologous recombination DNA repair-deficient tumors has engendered keen interest in developing synthetic lethality-based therapeutic strategies for ARID1A-mutated neoplasms." (PMID 36123603, 2022). "The ARID1A gene is commonly mutated in many types of cancer and is classified as a tumor suppressor." (PMID 34042312, 2022). "In this study, we found that ARID1A expression was negatively associated with tumor-infiltrating lymphocytes (TILs) and immune scores for ICIs." (PMID 36229854, 2022). "Recent studies have shown that loss of ARID1A expression sensitises tumours to CTLA4 and PD-1 immune checkpoint inhibition." (PMID 35393414, 2022). "Of note, biallelic ARID1A mutated tumours had the highest immune infiltration and PD-L1 scores, contrary to tumours with CTNNB1 mutation." (PMID 36613564, 2022). "According to a report on the association of ARID1A with tumor size in ccRCC, decreased ARID1A expression was associated with larger tumors (≥7 cm), high grades III and IV, and high stage III and IV (all: p = 0.03)." (PMID 35055428, 2022). "The loss of ARID1A, a frequently occurring alteration in malignant cells, was shown to result in the loss of the tumor suppressive function of TGF-β and increased cell migration." (PMID 36078038, 2022). "Genetic inactivation of ARID1A is widespread across several types of human cancer, and ARID1A-deficient tumor cells are very sensitive to robust epigenetic changes." (PMID 35883668, 2022). "ADAMTS10 and ARID1A mutations were observed simultaneously in the patient (P18) who had the largest tumor size (14.5 cm) among the 22 patients (size of tumors without mutation, mean: 6.2 cm, median: 5.5 cm)." (PMID 35055428, 2022). "It is noteworthy that tumours harbouring biallelic mutation in ARID1A showed the highest levels of CD3+ cells density (patients 2, 9 and 7), as well as of CD8+ (patients 2 and 7), and FOXP3+ (patients 2 and 7)." (PMID 36613564, 2022). "According to the current evidence, ARID1A variants are only expected to play a tumor suppressor effect CRC development." (PMID 35421925, 2022). "The CRC cell line SW480 showed a weak ability to form tumor spheres when cultured in 3D Matrigel on ultra-low attachment plates, and loss of ARID1A significantly enhanced this ability." (PMID 35715442, 2022). "ARID1A mutations have been previously implicated in tumor progression, chemoresistance, metastatic spread and activation of oncogenic signaling pathways such as PI3K and MAPK." (PMID 36117191, 2022). "As expected, a combination of low-dose irradiation and PARP inhibitor shows a synergistic cytotoxicity in ARID1A-deficient tumor cells in both in vitro and in vivo models." (PMID 36123603, 2022).
tumor (continued). "Recent discoveries indicate that defective control of enhancer activity is a principal mechanism underlying tumor suppression caused by ARID1A inactivation." (PMID 36435834, 2022). "We extended the analysis to a tumor tissue microarray and found that the ARID1A level was positively and negatively associated with the infiltration of CD8+ cells and the nuclear staining of P65 in PCa cells, respectively." (PMID 36435834, 2022). "ARID1A-deficient tumor-bearing mice exhibited increased mutational load as well as better lymphocytic tumor infiltration accompanied by increased PD- L1 expression in ovarian cancer." (PMID 36685594, 2022). "Transcriptional upregulation of HERVH is associated with mutations of several tumor suppressors, particularly ARID1A." (PMID 35715442, 2022). "ARID1A variations hint towards a promising tool for diagnostic tumor profiling and individualized therapeutic targets for CRC in the future." (PMID 35421925, 2022). "An analysis of mutational patterns within the ARID1A mutated tumor samples revealed UV-induced signature mutations." (PMID 35565222, 2022). "Among the SWI/SNF complex subunits, ARID1A has the highest frequency of mutation in cancers and is related to poor prognosis and high tumor activity." (PMID 36249060, 2022). "We found an association between ARID1A mutations and larger tumor sizes in this study (p = 0.004, r = 0.585)." (PMID 35055428, 2022). "ARID1A has emerged as a candidate “driver gene” tumor suppressor based on its frequent mutations in cancer cells, such as ovarian clear cell and endometroid cancers, as well as CRC." (PMID 35805024, 2022). "Investigation of subgroups upon their mutational profile showed that the tumor mutational load within the group of ARID1A mutated tumors is dependent on its co-mutations." (PMID 35565222, 2022). "Inconsistently, the majority of DEGs were found to be downregulated in the ARID1A-mut group in our study (46 vs 25), partly accounting for the tumor suppression effect of ARID1A deficiency in a wide range of cancer types." (PMID 36281289, 2022). "ARID1A is presumed to be a tumor suppressor based on loss-of-function mutational profiles in a broad variety of human cancers." (PMID 36435834, 2022). "Nevertheless, which molecular pathways are employed by ARID1A‐deficient tumours to survive and maintain DNA integrity in response to endogenous or exogenous events that result in DNA damage remains to be determined." (PMID 35167193, 2022). "These cells harbor mutations in BRCA2, PIK3CA, PTEN, and ARID1A genes, among others, associated with tumor initiation." (PMID 36438565, 2022). "Another common genetic feature of the two tested CUP tumors was the presence of alterations in ARID1A gene, which is a tumor suppressor gene encoding the DNA-binding subunit of the chromatin remodeler complex SWI/SNF." (PMID 34178989, 2021). "ARID1A is a tumour suppressor encoding a member of the SWI/SNF chromatin remodelling complex that regulates chromatin accessibility at regulatory elements and is involved in the maintenance of genomic stability and DNA repair." (PMID 33941236, 2021). "HDAC2 inhibition with SAHA re-localised HDAC2 to the cytoplasm and induced expression of PIK3IP1, which correlated with an improved prognosis for mice bearing ARID1A-mutated tumours." (PMID 33941852, 2021). "A study found that high heterogeneity of ARID1A expression was associated with increased tumor infiltrating lymphocytes (TILs) density in EOGC." (PMID 34513668, 2021).
tumor (continued). "HDACs are frequently overexpressed in SMARCB1-mutant tumours and in ARID1A-deficienct cancers, making them sensitive to HDAC inhibitors." (PMID 33941852, 2021). "Taken together, these results are suggestive that the increased presence of TAMs in the stroma and subsequent exclusion from the tumour cells in low-risk and ARID1A mutant tumours is indicative of a reduced immunosuppressive environment in these patients." (PMID 34359755, 2021). "Since the critical tumor-suppression effect of ARID1A has been unraveled, several studies have attempted to identify potential strategies for ARID1A-mutated cancer treatment based on synthetic lethal targets." (PMID 34671561, 2021). "In various types of cancer, chromatin remodeling factor, ARID1A, is frequently mutated and acts as a tumor suppressor." (PMID 34414106, 2021). "A number of studies have highlighted potential synthetic-lethal treatment strategies targeting tumours with loss of ARID1A." (PMID 34359755, 2021). "Consistent with the high mutation frequencies of ARID1A in many cancer types, ARID1A has been identified to exert a variety of tumor-suppressive functions during carcinogenesis." (PMID 34671561, 2021). "Previous studies have confirmed that ARID1A deficiency leads to the loss of the tumour suppressive function of TGF-β." (PMID 35127746, 2021). "This variant was further detected in the tumor sample from a different anatomic site (left ovary) in addition to PIK3CA and ARID1A variants previously identified in the tumor from the right ovary." (PMID 34660321, 2021). "We have reported that ARID1A mutations positively correlate with enhanced anti-tumor immunity in both experimental models and patient samples, and ARID1A-mutant tumors are sensitized to anti-PD-L1 treatment." (PMID 33419967, 2021). "ImE had strong immune infiltration, high DNA damage repair activity, high tumor mutation burden, prevalence of microsatellite instability, frequent ARID1A mutations, elevated PD-L1 expression, and favorable prognosis." (PMID 34079012, 2021). "ARID1A loss was observed in 12 cases, including two cases with focal loss affecting only solid areas of the tumor." (PMID 33435234, 2021). "This missing ARID1A expression partly describes clonal mutations and the presence of tumor heterogeneity." (PMID 33639673, 2021). "ARID1B is a preferred gene for the survival of ARID1A-mutant tumor cell lines, while loss of ARID1B in the background of ARID1A mutation destabilizes the SWI/SNF complex and impairs cell proliferation." (PMID 34671561, 2021). "Recent studies have showed that ARID1A loss is associated with improved response to immunotherapy across diverse tumor types." (PMID 33668727, 2021). "All these features indicate that tumor samples with ARID1A mutations have significantly denser cells and less stroma, which is consistent with the function of ARID1A as a tumor suppressor." (PMID 33869007, 2021). "Our immuno-molecular classification scheme supplemented with NSMP tumor sub-grouping based on the ARID1A and CTNNB1 status granted a more reliable risk assessment and it resulted to be particularly informative in the group of high-risk patients." (PMID 33668727, 2021).
tumor (continued). "Nearly all of the patients (30 of 31) with stage III and IV SWI/SNF‐deficient tumors died from their disease, except for one patient with stage IV ARID1A/1B‐deficient tumor that also harbored a POLE V411L mutation." (PMID 33125840, 2021). "Among these genes, ARID1A has the highest mutation frequency in many tumors, and is widely recognized as a tumor suppressor owing to the extensive loss-of-function mutations." (PMID 34689165, 2021). "ARID1A encodes BRG-associated factor 250a (BAF250a or p270), which has an important role in cell proliferation and tumor suppression." (PMID 33803806, 2021). "ARID1A is presumed to be a tumor suppressor based on loss-of-function mutational profiles observed in many cancers, including gastrointestinal cancers." (PMID 34249744, 2021). "The diverse antitumor immune signatures are more highly enriched in ARID1A-mutated GC than in ARID1A wild-type GC, which is associated with higher tumor mutation burden and lower tumor aneuploidy level." (PMID 34671561, 2021). "When ARID1A mutation status was considered, we identified that mutant cases showed the simultaneous ‘tumour-exclusion’ of both CD68 + TAMs and CD8 + cytotoxic T cells." (PMID 34359755, 2021). "Notwithstanding findings of ARID1A as a key tumor suppressor and potential therapeutic target, important gaps in knowledge remain concerning ARID1A mutations and deficiency in tumors." (PMID 34671561, 2021). "Once tumor cells possess ARID1A mutations, subsequent ATR inhibition initiates premature mitotic entry, genomic instability, and apoptosis." (PMID 33513745, 2021). "Recent studies revealed that ARID1A-deficient tumors are sensitive to PARP inhibitors and ATR inhibitors, and the combination of PARP inhibitors and ionizing radiation in the treatment of tumor cells with ARID1A deficiency has a selective and high efficiency." (PMID 34671561, 2021). "Neoplasms formed by ARID1A deficiency have increased mutation rates, elevated tumor-infiltrating lymphocytes, and PD-L1 expression." (PMID 33608032, 2021). "Loss of ARID1A tumour suppressive functions triggers cancer development through perturbations of DNA-damage response and cell-cycle pathways." (PMID 33941852, 2021). "Integrated WGS and tNGS analysis clearly distinguished this tumor type from EBV-negative DLBCL due to frequent mutations in ARID1A (45%), KMT2A/KMT2D (32/30%), ANKRD11 (32%), or NOTCH2 (32%)." (PMID 34039950, 2021). "Of note, there were 36 of 72 (50%) tumors with ARID1A gene mutation showed tumor stage IV and 52 of 79 (66%) cases with ARID1A mutations presented with T3/T4." (PMID 33344089, 2020). "Two independent disrupting mutations in ARID1A were found to be clonal in each of 16/64 tumours (25%) and only four tumours had one clonal and one subclonal inactivating event." (PMID 31949146, 2020). "The most affected marker was ARID1A, whereby 47% of the cases had a loss of staining in tumor cells as well as stromal tissue and lymphocytes, which are the internal controls, followed by PMS2 (12%), and BRG1 (14%)." (PMID 32677969, 2020). "It is likely that ARID1A mutation occurred in clones of cells within the tumor, resulting in a heterogeneous staining pattern of ARID1A expression." (PMID 33344089, 2020). "ARID1A is generally known as a tumor suppressor, and its loss is associated with increased migration, invasion, and metastasis." (PMID 33268834, 2020). "ARID1A protein is typically deficient in oncogenic tissues, and therefore is suspected to possess the tumor suppressor activity of the complex." (PMID 32334542, 2020).